HK1 (hexokinase 1)
Diseases named in the same sentence as HK1 in open-access papers (continued):
Sharing a sentence is not in itself a finding about the gene and the disease.
lung carcinoma (14 papers, 2015 to 2025). "The western blot results further confirmed that the overexpression of miR-302a inhibited the expression of HK1; conversely, the miR-302a inhibitor promoted HK1 expression, indicating that HK1 is the target gene of miR-302a in lung cancer cells." (PMID 41219936, 2025). "Taken together, the results of rescue experiments revealed that NR6A1 promotes glucose metabolism and proliferation through miR-302a/HK1 in lung cancer cells." (PMID 41219936, 2025). "The analysis of the TCGA database with TIMER showed that HK3 is significantly downregulated in lung cancer tissues, while HK1 and HK2 are significantly upregulated at the same time." (PMID 32508023, 2020). "Although HK1+HK2+ lung cancer H460 cells are resistant to this therapeutic combination, isogenic HK1KOHK2+ cells are sensitive to this therapy." (PMID 29988332, 2018). "To determine whether HK1−HK2+ cancers of other origins will be sensitive to HK2 inhibition, we created isogenic HK1−HK2+ cells from HK1+HK2+ H460 lung cancer cells." (PMID 29988332, 2018). "Likewise, glyceraldehyde-3-phosphate dehydrogenase and hexokinase 1 genes were up-regulated by > 3-fold in PLACs and were also reported to be up-regulated in human lung cancers." (PMID 27602772, 2016). "Through a series of experiments, including bioinformatics analysis, dual-luciferase reporter gene expression, RT‒qPCR and Western blot analysis, we proved that NR6A1 could inhibit miR-302a in lung cancer cells, thereby indirectly promoting the expression of HK1." (PMID 41219936, 2025). "In addition, we used CRISPR Cas9 HK1 deletion to create isogenic HK1−HK2+ and HK1+HK2+ H460 lung cancer cell lines." (PMID 29988332, 2018). "However, HK1+HK2+ cancer cell lines from a variety of cancers (liver, breast, colon, prostate, ovary, lung), including the lung cancer H460 cell line, are resistant to HK2 silencing alone or the synthetic lethality of the shHK2/DPI/PER." (PMID 29988332, 2018).
ovarian cancer (14 papers, 2017 to 2024). A primary or metastatic malignant neoplasm involving the ovary. "Loss of hexokinase 1 (HK1), a well-characterized enzyme engaged in glycolysis, can sensitize ovarian cancer to high-dose metformin." (PMID 36147929, 2022). "We tested the isoenzyme-specific regulatory roles of HKs in ovarian cancer cells by examining the effects of the deletions of HK1 and HK2 in TOV-112D ovarian adenocarcinoma cells." (PMID 34895333, 2021). "The HK1 expression in ovarian cancer was both necessary and sufficient to sustain tumor progression, particularly when the cells were exposed to glucose starvation in parallel with high-dose metformin treatment." (PMID 34895333, 2021). "In ovarian cancer, HK1 alone is frequently a dominant hexokinase isoenzyme and appears to be sufficient to sustain tumor progression." (PMID 34895333, 2021). "Despite that, we revealed that HK2 and HK1 levels correlate in patient-derived ovarian epithelial cancer cells as well as fibroblasts from normal adjacent ovaries." (PMID 34895333, 2021). "The expression of HK1 has been shown upregulated trend which is beneficial to cancer cell proliferation by enhancing glycolysis in some cancer types, including pancreatic malignant tumor, bladder carcinoma, and ovarian malignant tumor." (PMID 37741973, 2023). "Key substances in the glucose metabolism process of ovarian cancer cells, including glucose transporter 1, hexokinase 1 (HK1), hexokinase II (HK2), etc., promote the proliferation and metastasis of tumor cells through a variety of downstream target genes and signaling pathways." (PMID 37681030, 2023). "Furthermore, HK1 may serve as a standalone biomarker for the dismal outcome experienced by ovarian cancer patients, as suggested by both univariate and multivariate analyses." (PMID 38967113, 2024). "Therefore, we assumed that HK1 plays an important role in ovarian cancer onset and progression." (PMID 34895333, 2021). "The majority of cell lines expressed more HK1 transcripts than HK2 (HK1:HK2 ratio 2.3 ± 0.4), and the levels of HK transcripts correlated with one another, which we further confirmed for selected three ovarian cancer cell lines at the protein level." (PMID 34895333, 2021). "We found various expressions of HK1 and HK2 mRNA and protein levels in ovarian cancer cells." (PMID 39114948, 2024). "To determine whether treatment with GP‐2250 affects upstream metabolites of glycolysis, we examined HK1 and HK2 mRNA and protein expression and activity levels in ovarian cancer cell lines." (PMID 39114948, 2024). "We found that the HK1 depletion (but not the HK2 depletion) sensitized ovarian cancer cells to high-dose metformin during glucose starvation." (PMID 34895333, 2021). "The HK1 deletion (but not HK2 deletion) suppressed the growth of xenotransplanted ovarian cancer cells and nearly abolished the tumor growth when the mice were fed the glucose-free diet." (PMID 34895333, 2021).
melanoma (11 papers, 2016 to 2025). A malignant, usually aggressive tumor composed of atypical, neoplastic melanocytes. "Hypoxic conditions upregulate HK1 (hexokinase 1), a critical glycolytic enzyme, which has been linked to poor prognosis in malignant melanoma, head and neck squamous cell carcinoma, and oral squamous cell carcinoma." (PMID 37576511, 2023).
non-small cell lung carcinoma (11 papers, 2007 to 2025). A group of at least three distinct histological types of lung cancer, including non-small cell squamous cell carcinoma, adenocarcinoma, and large cell carcinoma. "The aim of this study was to investigate the effect of lactic acid down-regulation of hexokinase 1 (HK1) on non-small cell lung cancer (NSCLC) through histone lactylation by Mendelian randomization (MR)." (PMID 41054045, 2025). "Glycolytic enzymes (HK-1, PKM2) demonstrated down-regulation, while TCA cycle enzymes (SDHA, IDH3G) revealed up-regulation in their mRNA expressions in non-small-cell lung cancer during in vitro assays." (PMID 40755753, 2025). "Lactate also regulates cellular metabolism at least in part through down-regulating HK-1 (glycolytic enzyme) and up-regulating IDH3G (TCA cycle enzyme) gene expression mediated by histone lactylation in non-small cell lung cancer." (PMID 38200523, 2024).
glioblastoma (10 papers, 1996 to 2024). The most malignant astrocytic tumor (WHO grade IV). "Although Hexokinase 1 can contribute to cancer, Hexokinase 2 is more frequently overexpressed in various cancers including colorectal, liver, cervical, and metastatic breast cancer and glioblastoma, and its overexpression is associated with a worse survival." (PMID 36697489, 2023). "A cytoplasmic lncRNA LINC00470 involving fused in sarcoma (Fus), AKT, and HK1 pathway promotes glycolysis in glioblastoma cells by repressing HK1 ubiquitination." (PMID 31850189, 2019). "Moreover, Chip-seq analysis in glioblastoma cells has demonstrated that glycolysis and pyruvate-related genes, such as hexokinase 1 (HK1), ENO2 and PCK2, are among the PRC-active target genes." (PMID 36135315, 2022). "HK1 is highly expressed in normal brain and low-grade gliomas, whereas HK2 is overexpressed in developing embryos and glioblastoma (GBM) tissue." (PMID 37108511, 2023).
Sepsis (9 papers, 2021 to 2026). Sepsis is defined as life-threatening organ dysfunction caused by a dysregulated host response to infection. "For example, inactivation of hexokinase 1 (HK1), the first rate-limiting enzyme of the glycolytic pathway, suppressed macrophage proinflammatory responses and LPS-induced sepsis in mice." (PMID 34660743, 2021).
Arthritis (8 papers, 2008 to 2023). Inflammation of a joint. "Cellular inflammatory response in the chronic arthritis model, as shown by the histopathological arthritis score, was significantly reduced in HK-1-deficient mice." (PMID 33519457, 2020). "The present work focused on investigating the involvement of HK-1 in arthritis models of distinct mechanisms with special emphasis on pain, nociceptive sensory neurons and the molecular mechanism of action." (PMID 33519457, 2020). "In inflammatory pain and arthritis, a pro-inflammatory component is also likely to contribute to its action, since HK-1 expression was described in the immune system as well and Tac4 deficiency also alleviated experimental lung inflammation." (PMID 32331300, 2020). "Here we provide the first evidence for an important role of HK-1 in pain transmission using different arthritis models." (PMID 33519457, 2020). "Despite little information about HK-1 in pain and arthritis, the best-known member of the tachykinin family, SP, and the NK1R have been thoroughly investigated in these conditions (Zieglgänsberger, 2019)." (PMID 33519457, 2020). "The present study provides the first evidence that HK-1 increases inflammatory pain in the chronic phase of CFA-induced arthritis." (PMID 23626716, 2013). "Therefore, we investigated the role and mechanism of action of HK-1 in arthritis models of distinct mechanisms with special emphasis on pain." (PMID 33519457, 2020). "Based on the present results, identification of the target and the precise signalling pathways, then antagonizing the actions of HK-1 might be a new perspective for the treatment of arthritis." (PMID 23626716, 2013). "Our current results show that HK-1 mediates both the early inflammatory pain, and the late neuropathic-type pain in arthritis observed during the 3rd week of the K/BxN experiment, while other studies showed the activation of spinal microglia in experimental arthritis." (PMID 33519457, 2020).
cervical carcinoma (8 papers, 2016 to 2025). A carcinoma arising from either the exocervical squamous epithelium or the endocervical glandular epithelium. "In fact, quenching HK1 impaired aerobic respiration and increased glycolysis without influencing ATP production, but it did cause an epithelial–mesenchymal phenotypic change in cervical cancer cells, which sped up tumor growth and metastasis in both in vitro and in vivo tests." (PMID 38967113, 2024). "In contrast to that in normal tissues, increased expression of HKs such as HK1 has been observed in many types of cancer, such as cervical cancer and bile duct carcinoma." (PMID 41219936, 2025). "The knockdown of HK1 induced energy metabolism disorders and accelerated the invasion of cervical cancer HeLa cells." (PMID 40559415, 2025). "To analyse the functional role of HK in tumor progression, we established several stable HK1 or HK2 knockdown lines in human cervical carcinoma HeLa cells using the RNAi-mediated gene silencing approach." (PMID 29721175, 2018). "In cervical carcinoma cells, the HK1 but not HK2 knockdown induced a phenotypic change characteristic of epithelial-mesenchymal transition, which accelerated tumor growth and metastasis." (PMID 36335239, 2022). "In cervical carcinoma cells, the HK1 but not HK2 knockdown induced a phenotypic change characteristic of epithelial-mesenchymal transition, which accelerated tumor growth and metastasis both in vitro and in vivo analyses." (PMID 29721175, 2018). "In this study, we first showed that HK1 but not HK2 knockdown induced a typical EMT switch in human cervical cancer cells." (PMID 29721175, 2018).
bladder cancer (7 papers, 2017 to 2025). "The overexpression of circST6GALNAC6 inhibits glycolysis and the proliferation of bladder cancer cells by promoting the degradation of hexokinase 1 (HK1)." (PMID 40710359, 2025). "In bladder cancer, UMUC-3 cells show high HK2 expression and low HK1 expression; the inhibiting HK2 showed reduced glucose consumption, lactic acid production, and glycolysis." (PMID 35265223, 2022).
colon carcinoma (7 papers, 2014 to 2025). "To further demonstrate the role of HK1, we overexpressed HK1 in the human colon cancer cell line HT29." (PMID 40436833, 2025).
Hyperglycemia (7 papers, 2014 to 2024). An increased concentration of glucose in the blood. "In these cells, HK1-mediated glucose metabolism prevents glycolytic overload and unscheduled glycolysis when intracellular glucose concentration is increased in hyperglycemia." (PMID 38292764, 2023). "We observed significant downregulation of Mafa, Ins1, and Ins2 mRNAs, and significant upregulation of Aldob, Slc5a10, Wnt5b, Hk1, and Tnfrsf11b mRNAs, suggesting that the molecular defect results directly from the loss of Cnot3, rather than to hyperglycemia." (PMID 32859966, 2020). "Pharmacological inhibition of HK1 and PFKP effectively prevents sustained inflammation related to hyperglycemia and promotes neutrophil clearance." (PMID 38049662, 2024). "Studies of the sciatic nerve of healthy control and streptozotocin (STZ)-induced diabetic rats indicate a high glucose content of the nerve, indicating that HK1 and HK2 are saturated in both euglycemia and hyperglycemia." (PMID 38292764, 2023). "Unlike vascular cells, the intracellular concentration of glucose in myocytes and adipocytes is usually relatively low: HK1 is saturated by glucose euglycemia and hyperglycemia, whereas HK2 is not." (PMID 38292764, 2023). "Importantly, the HK1/HK2 ratio was positively correlated with resting glucose consumption (r = 0.63), and negatively correlated with the change in glucose consumption during hyperglycemia (r = −0.63)." (PMID 39314314, 2024). "Simulations of glucose transport revealed that, unlike hexokinase 1, HK2 is not saturated at euglycemia, thus accommodating increased AG during hyperglycemia." (PMID 39314314, 2024). "Our simulations of glucose transport showed that, unlike HK1, HK2 is not saturated at euglycemia and can accommodate increases in flux by upwards of 50% during hyperglycemia." (PMID 39314314, 2024). "Both HK1 and HK2 expessed in these cell types are saturated with glucose, and yet, the flux of glucose metabolism is increased without increased HK expression in hyperglycemia." (PMID 38292764, 2023).
hyperinsulinism (7 papers, 2020 to 2026). Abnormally high levels of insulin in the blood. "Discovering variants in 89 families confirms HK1 as a major cause of hyperinsulinism and highlights the important role of the non-coding genome in human monogenic disease." (PMID 40033430, 2025). "Non-coding variants within the HK1 cis-regulatory region cause hyperinsulinism of variable severity ranging from neonatal-onset, treatment-resistant disease to being asymptomatic into adulthood." (PMID 40033430, 2025). "We recently reported non-coding variants in a cis-regulatory element of the beta-cell disallowed gene hexokinase 1 (HK1) as a novel cause of congenital hyperinsulinism." (PMID 40033430, 2025). "We demonstrated that the variants result in a loss of repression of HK1 in pancreatic beta-cells, thereby causing insulin secretion and congenital hyperinsulinism." (PMID 36333503, 2022). "Furthermore, the mendelian randomization analysis suggested a causal relationship of DNA methylation in HK1 with HbA1c levels, supporting previous findings of HK1’s GWAS associations with HbA1c and HK1 pathways involving glucose, insulin signaling and hyperinsulinemia." (PMID 37679740, 2023). "Many upregulated genes related to glucose metabolism were upregulated by hyperinsulinemia, such as G6pc3, Hk1, Pck2 and Aldoa, some of which were reverted to baseline by starvation." (PMID 34921686, 2022). "We screened the HK1 cis-regulatory region in 1761 probands with hyperinsulinism of unknown aetiology who had been referred to one of three large European genomics laboratories." (PMID 40033430, 2025). "Yet, HK1 expression, which is normally disallowed in the beta cells, may cause significant fasting hyperinsulinism even in low-grade mosaic HK1-CHI, in keeping with the very high glucose affinity of hexokinase 1 (Km<0.05 mM), compared to a physiological Km of 5 mM for glucokinase (hexokinase 4)." (PMID 41561050, 2025).
lung adenocarcinoma (6 papers, 2022 to 2025). A carcinoma that arises from the lung and is characterized by the presence of malignant glandular epithelial cells. "We confirmed that high expression of NR6A1 in lung adenocarcinoma tissues was significantly positively correlated with HK1 and p-mTOR expression." (PMID 41219936, 2025). "In summary, our data indicate that NR6A1 plays an oncogenic role by reprogramming glycolysis via the miR-302a/HK1 axis in lung adenocarcinoma." (PMID 41219936, 2025). "However, while integrating external database findings with our tissue microarray results (n = 30) has preliminarily revealed the expression profile of NR6A1 in lung adenocarcinoma and its correlation with HK1, the sample size remains constrained." (PMID 41219936, 2025). "Compared with those in the adjacent noncancerous tissue (ANCT) group, high expression of NR6A1 was observed in the lung adenocarcinoma (LUAD) group, whereas the protein levels of HK1 and p-mTOR were high in the LUAD group." (PMID 41219936, 2025). "The amplified products were subjected to agarose gel electrophoresis, and six samples all gave clear bands in the correct region indicated by the marker, confirming that the six predicted six-HRGs (STC1, PFKL, HK1, PDK3, SLC2A1, XPNPEP1) were all expressed in lung adenocarcinoma A549 cells." (PMID 37576511, 2023).
Obesity (6 papers, 2017 to 2024). Accumulation of substantial excess body fat. "Hexokinase-1 mediated glycolysis regulates the NLR Family Pyrin Domain Containing 3 (NLRP3) inflammasome, a multiprotein complex implicated in obesity-related inflammation as well as several pulmonary diseases." (PMID 30990817, 2019).
Alzheimer disease (5 papers, 2013 to 2025). A progressive, neurodegenerative disease characterized by loss of function and death of nerve cells in several areas of the brain leading to loss of cognitive function such as memory and language. "HK1 variants have been identified in developmental encephalopathies, and Alzheimer’s disease murine model." (PMID 40779003, 2025).
asthma (5 papers, 2018 to 2022). "In summary, we discovered a novel epigenetic association with adolescent asthma at cg16658191 within HK1, whose DNAm and expression levels in cord blood were also associated with infant wheeze without cold." (PMID 31367216, 2019). "Due to the wide spread of HK-1 in the body, and its preferential affinity to the NK-1 tachykinin receptor, it has been implicated in many diseases (reviewed elsewhere,) including asthma and possibly COPD." (PMID 30081920, 2018). "Hence, reverse causation in which asthma may result in differential methylation of HK1 cannot be excluded." (PMID 31367216, 2019). "Though DNAm at cg16658191 may, in part, be a marker of high eosinophil counts in adult blood and nRBCs in cord blood, we found that, in addition to the relationship between DNAm and asthma, HK1 expression was strongly and significantly associated with infant wheeze even after cell-type adjustments." (PMID 31367216, 2019). "It is also important to point out that the relationships we observed between DNAm and expression of HK1 in cord blood with infant wheeze, cannot be directly extrapolated to asthma." (PMID 31367216, 2019). "We identified that lower DNAm at cg16658191 within the 1st exon of HK1 as a marker of current asthma." (PMID 31367216, 2019). "This provides a possible mechanism through which HK1 epigenetic regulation and expression by immune cells may be involved in asthma and wheeze etiology." (PMID 31367216, 2019). "It is unclear whether DNAm patterns of HK1 in cord blood are informative for the later development of asthma, although our findings provide evidence that lower DNAm and increased expression of HK1 in cord blood are associated with wheezing in the 1st year of life." (PMID 31367216, 2019).